MIR548M (microRNA 548m)
Synonyms: hsa-mir-548m; MIRN548M
Gene: MicroRNA gene on chromosome X (95,063,141 to 95,063,226, reverse strand). Ensembl gene ENSG00000221187.
Gene Ontology:
Biological process: miRNA-mediated post-transcriptional gene silencing
Cellular component: RISC complex